MIR6510 (microRNA 6510)
Synonyms: hsa-mir-6510; mir-6510
Gene: MicroRNA gene on chromosome 17 (41,517,164 to 41,517,217, reverse strand). Ensembl gene ENSG00000283796.
Homologues: Orthologues: chimpanzee MIR6510 (100% identical).